VIL1 (villin 1)
Diseases named in the same sentence as VIL1 in open-access papers:
VIL1 is named in the same sentence as 43 diseases in open-access papers, as found by Europe PMC text mining. Sharing a sentence is not in itself a finding about the gene and the disease. The quoted sentences say what the papers report.
colitis (3 papers, 2018 to 2025). Inflammation of the colon. "Remodeling of the actin cytoskeleton underlies the membrane dynamics necessary for cell migration and disruption of actin remodeling is sufficient to cause chemically-induced colitis in Vil1−/− mice." (PMID 30279225, 2018). "NSD2fl/fl‐Vil1‐Cre mice showed fewer symptoms of colitis, including unformed stool, rectal bleeding, and decreased colon length." (PMID 38400589, 2025). "To investigate the impact of AhR‐mediated induction of mBD‐1 expression on colitis, we generated conditional AhR knockout mice in vil1‐expressing CECs using the cre‐flox system." (PMID 40410944, 2025). "Additionally, NSD2fl/fl‐Vil1‐Cre mice showed fewer symptoms of colitis, including unformed stool, rectal bleeding, and decreased colon length." (PMID 38400589, 2025). "NSD2fl/fl‐Vil1‐Cre mice also exhibited fewer colitis symptoms and fewer tumors." (PMID 38400589, 2025).
colorectal cancer (3 papers, 2012 to 2025). A primary or metastatic malignant neoplasm that affects the colon or rectum. "Our results showed that the concentrations of IL‐6, TNF‐α, and TGF‐β1 in the serum of NSD2fl/fl‐Vil1‐Cre mice with colorectal cancer were much lower than those in the serum of WT mice." (PMID 38400589, 2025).
cervical adenocarcinoma (2 papers, 2020 to 2023). An adenocarcinoma arising from the cervical epithelium. "VIL1 has been identified as a novel marker for poor response to radiation treatment for patients with cervical adenocarcinoma." (PMID 37626856, 2023). "The results of co-expression analysis shows that VIL1 is co-expressed with many genes up-regulated in cervical adenocarcinoma." (PMID 33024199, 2020). "The co-expression analysis showed that VIL1 was co-expressed with multiple genes, which are also dysregulated in cervical adenocarcinoma." (PMID 33024199, 2020). "This combined miR-192-5p/HNF1A-AS1/VIL1 panel achieved greater AUC value than any single candidate detection, indicating a promising biomarker pattern for discriminating cervical adenocarcinoma from normal cervix." (PMID 33024199, 2020). "Our identification of miR-192-5p/HNF1A-AS1/VIL1 panel offers an exciting novel insight into the development of cervical adenocarcinoma." (PMID 33024199, 2020). "Consistent with other reports, we observed significant upregulation of VIL1 mRNAs in human cervical adenocarcinoma tissues." (PMID 33024199, 2020). "In summary, we have determined specific mRNA, lncRNA, and miRNA signatures between cervical adenocarcinoma and normal cervix and identified a novel panel consisting of miR-192-5p, HNF1A-AS1 and VIL1 for discriminating cervical adenocarcinoma form normal tissues." (PMID 33024199, 2020). "Third, we examined the expression signatures of the 6 putative mRNAs/ncRNAs in another independent cohort of cervical adenocarcinoma tissues and identified a panel containing miR-192-5p, HNF1A-AS1 and VIL1 as the effective biomarker set for cervical adenocarcinoma." (PMID 33024199, 2020). "The Receiver Operating Characteristic (ROC) curve analysis indicated that combination of miR-192-5p, HNF1A-AS1, and VIL1 yielded a better performance (AUC = 0.911) than any single molecule -and could serve as potential biomarkers for cervical adenocarcinoma." (PMID 33024199, 2020). "Using the AUC value of > 0.70 as a cutoff for high significance, we identified VIL1, HNF1A-AS1, and miR-192-5p as specific biomarkers for the cervical adenocarcinoma group, suggesting the valuable diagnostic potential of these 3 candidates in cervical adenocarcinoma patients." (PMID 33024199, 2020). "Thus, we propose that VIL1 might be a candidate of HPV18-related oncogene in cervical adenocarcinoma." (PMID 33024199, 2020). "Further logistic regression analysis identified combination of miR-192-5p/HNF1A-AS1/VIL1 panel and TCT tests to achieve greater AUC (0.964) than the TCT test or miR-192-5p/HNF1A-AS1/VIL1 panel detection, suggesting a potential biomarker for cervical adenocarcinoma." (PMID 33024199, 2020).
colon cancers (2 papers, 2024). "Amongst the CDX2-correlated genes from human colon cancers, those downregulated in proximal organoids with Cdx2 loss included the key epithelial regulatory genes, such as Hnf4A, Satb2, and Vil1." (PMID 38360902, 2024). "In Vil1-CreER;BrafLSL-V600E/+;Tgfbr1fl/fl mice, the proximal colonic tumors exhibit fetal intestinal signature." (PMID 38921956, 2024).
colorectal tumors (2 papers, 2022 to 2025). "Compared with wild‐type (WT) control mice, NSD2fl/fl‐Vil1‐Cre mice exhibited significantly decreased tumor numbers, histopathological changes, and cytokine expression in colorectal tumors." (PMID 38400589, 2025).
gastric cancer (2 papers, 2017 to 2025). A primary or metastatic malignant neoplasm involving the stomach. "Thus, in initial studies, we evaluated CDX2 expression and the expression of another epithelial cell differentiation marker, VIL1, in human gastric cancer cell lines before and after treatment with HpSlyD." (PMID 28536478, 2017). "This concept is supported by the observation that a large proportion of TTF-1-positive colonic or gastric cancers also showed an immunohistochemical expression of at least one of the following markers: SATB2, CK20, FABP1, and Villin-1." (PMID 40564811, 2025).
Insulin resistance (2 papers, 2013 to 2015). Increased resistance towards insulin, that is, diminished effectiveness of insulin in reducing blood glucose levels. "Expression levels of several genes relevant to intestinal extracellular matrix, including those coding for mucin proteins as well as for metalloproteinase 7 and villin 1, were altered in presence of insulin resistance." (PMID 26376914, 2015).
intestinal polyposis (2 papers, 2025). "After treatment with antibody (UCB Ab7326), mice showed a reversion of the characteristic Vil1/Grem1 pan‐intestinal polyposis phenotype with an increase in mean survival." (PMID 40212011, 2025). "This resulted in a remarkable reversion of the characteristic Vil1-Grem1 pan-intestinal polyposis phenotype." (PMID 40467544, 2025). "Vil1/Grem1 mice were produced, which displayed classical features of HMPS, including pronounced pan‐intestinal polyposis and lesions that phenocopy the histology of human patients, including the formation of ectopic crypts." (PMID 40212011, 2025).
liver cancer (2 papers, 2020 to 2021). An epithelial or non-epithelial malignant neoplasm that arises from the liver. "We also detected a clear upregulation of several liver cancer marker genes such as AFP, GPC3, SAA1, and VIL1 in transformed iHeps and in CMT + sgTP53 tumors compared to control fibroblasts; AFP was also found among the most enriched genes in both CMT + sgTP53- and CMT-transformed iHeps." (PMID 34302118, 2021).
adenoma (1 paper, 2024). A neoplasm arising from the epithelium. "In mice, compared to the neighboring normal mucosa or stroma in the tumor, Fak protein levels were substantially decreased in carcinomas in the colon and adenomas/polyps in the small intestine (SI) in Vil1-Cre;BRAFLSL-V600E/+ (BC) mice." (PMID 38921956, 2024).
autosomal dominant polycystic kidney disease (1 paper, 2023). Autosomal dominant form of polycystic kidney disease. "This suggests that envoplakin, periplakin, and villin-1 may be used as biomarkers to differentiate between autosomal dominant polycystic kidney disease (ADPKD) patients with or without CKD." (PMID 37510273, 2023).
co-infection (1 paper, 2025). "Moreover, the biomarkers of glandular intrinsic components (TFF1) and tumor-associated genes (VIL1 and Lgr5) were significantly upregulated, providing further evidence that host aberrations and tumor progression are triggered by co-infection of EBV with H. pylori." (PMID 40833108, 2025). "Consistently, the results showed that NGOs displayed a significant upregulation of TFF1, VIL1, and Lgr5 at 24 h after co-infection of H. pylori with EBV and a downregulation of CD44 and Axin 2 compared to the H. pylori or EBV-alone groups." (PMID 40833108, 2025). "Using quantitative PCR analysis, the results showed that the expressions of Lgr5 and VIL1 gradually increased, peaking at 48 and 72 h in the co-infection of the EBV and H. pylori groups, respectively." (PMID 40833108, 2025). "We found that the co-infection of H. pylori and EBV induced a significant structural change and upregulated the expression of TFF1, VIL1, and Lgr5 to promote cell proliferation and tissue morphogenesis." (PMID 40833108, 2025).
COVID-19 (1 paper, 2023). A disease caused by infection with severe acute respiratory syndrome coronavirus 2. "Four of the five intestine-enriched proteins, i.e., ZG16, NLRP6, APOA4, and VIL1, showed decreased levels in serum of COVID-19 patients, whereas only CDHR2, a microvillar protein, showed elevated levels." (PMID 37739942, 2023).
gastric diseases (1 paper, 2017). "Our results show that HpSlyD induces CDX2 and VIL1 expression mediated through TCTP and contributes to IM and the development of gastric diseases." (PMID 28536478, 2017).
Hypoglycemia (1 paper, 2021). A decreased concentration of glucose in the blood. "Decreased protein expression of SLC2A2, VIL1, and EZR due to PAD probably impair glucose absorption system, which may provide a possible explanation for fasting hypoglycemia that is seen." (PMID 34193047, 2021).
Immunodeficiency (1 paper, 2021). Failure of the immune system to protect the body adequately from infection, due to the absence or insufficiency of some component process or substance. "ABPs such as gelsolin, Tβ4, filamin, villin-1, gelsolin, profilin-1, SYNPO, and cortactin are abnormally expressed in certain inflammatory environments, where they inhibit or induce immunodeficiency inflammation." (PMID 34194957, 2021).
intestinal cancer (1 paper, 2022).
metastatic colorectal cancer (1 paper, 2012). "All these data demonstrated that the model of GAPDH, VIL1 and CD45 biomarker combination is a robust method for the detection of CTC from metastatic colorectal cancer patients." (PMID 22304365, 2012).
polyposis (1 paper, 2025). "Although the resultant phenotype was less profound than in the germline Vil1-Grem1 model, all Villin-CreERT2;Rosa26Grem1 animals developed polyposis with the initial establishment of ectopic crypts on the villi containing aberrantly proliferating Sox9(+) stem/progenitor cells." (PMID 40467544, 2025).
ulcers (1 paper, 2021). "Biopsy ulcers in Vil1-Grem1 animals wererapidly covered by WAE, whereasepithelial Bmp4 expression inVil1-Cre;Rosa26Bmp4 micedelayed coverage by WAE and retarded closure." (PMID 33819486, 2021).
tumor (25 papers, 2012 to 2025). "Both ICIs were applied as monotherapy to tumor-free Msh2loxP/loxP; TgTg(Vil1-cre mice and overall survival was analyzed along with a longitudinal assessment of immunologic changes in the periphery and bone marrow." (PMID 40674934, 2025). "Consistent with our previous findings, membrane expression of VIL1 expression was significantly higher in well/moderately differentiated (low grade) compared to poorly differentiated (high grade) tumours." (PMID 41105300, 2025). "We next assessed expression levels of the brush border protein VIL1, which as expected, was highest in the apical membrane of tumour cells." (PMID 41105300, 2025). "An animal model consisting of tumor-bearing Msh2loxP/loxP;TgTg (Vil1-cre) mice treated with an anti-PD-1 and anti-LAG-3 combination showed reduced circulating Tregs and lower levels of Tex cells positive for CTLA-4, LAG-3, and PD-1." (PMID 39273452, 2024). "To address the functional significance of FAK downregulation in BRAFV600E-induced serrated tumor formation/initiation, we generated the Vil1-Cre;BRAFLSL-V600E/+;Ptk2fl/fl (FBC) mice." (PMID 38921956, 2024). "Histological examination revealed that HCT116EHF + CDX1 tumours were more differentiated, evidenced by increased gland formation and expression of the differentiation markers VIL1 and KRT20, compared to HCT116EV, HCT116EHF or HCT116CDX1 tumours." (PMID 35606410, 2022). "Expression was compared by signal intensity in microarrays and staining of histological sections of these tumours using antibodies to p63, Krt5, Krt7 and Vil1." (PMID 26783136, 2016). "Consequently, clinicopathological characteristics and the expression levels of GSN, SCIN, CAPG, VILL, VIL1, SVIL, and FLII were found to be closely associated with tumor stages in EC." (PMID 39964147, 2025). "Multiple types of cells were found within the tumor organoid in a heterogeneous manner, such as paneth cells expressing Lysozyme (Lysz) and epithelial cells expressing Villin 1 (Vill), while a lower abundance of Mucin2 (Muc2)-expressing goblet cells were observed in the tumor organoids." (PMID 38954022, 2024). "Of the LG xenografts, 79% and 78% displayed positive staining for VIL1 and KRT20, respectively, compared to 12% and 33% of HG tumours (P < 0.001 and P < 0.0001, for VIL1 and KRT20 respectively, Fisher’s exact test)." (PMID 40473896, 2025). "In Vil1-Cre;BRAFLSL-V600E/+;Ptk2fl/fl mice, Fak deletion maximized BRAFV600E’s oncogenic activity and increased cecal tumor incidence to 100%." (PMID 38921956, 2024). "To determine the tumour suppressive effects of DUSP5 in the intestinal epithelium in vivo, we crossed Vil1-DUSP5Tg with ApcMin/+ mice." (PMID 29379130, 2018). "Msh2loxP/loxP; TgTg(Vil1-cre mice without clinical signs of tumor development (i.e. age <12 weeks) received repeated applications (n = 8, 28-day interval) of anti-PD-L1, anti-LAG-3 (2.5 mg/kg bw, i.p.)or isotype (anti-IgG1, 2.5 mg/kg bw, i.p.)." (PMID 40674934, 2025). "The aim of this study was to prospectively validate a gene expression panel (composed of GAPDH, VIL1, CLU, TIMP1, TLN1, LOXL3 and ZEB2) for detecting circulating tumor cells (CTCs) as prognostic and predictive tool in blood samples from 94 metastatic CRC (mCRC) patients." (PMID 28608814, 2017).
cancer (6 papers, 2012 to 2025). A tumor composed of atypical neoplastic, often pleomorphic cells that invade other tissues. "In conclusion, we demonstrated that H. pylori infection leads to increased expression of CDX2 and VIL1 and that TCTP enhances this expression, and these changes were associated with the development of IM and cancer in the gastric mucosa." (PMID 28536478, 2017). "Among genes downregulated by clofibrate, the major part belonged mainly to functional groups: “cancer” (STIP1, HNRNPA1, VIL1, and CDH1) and “cellular assembly and organization” (CLASP1 and MACF1)." (PMID 22619672, 2012).
infection (2 papers, 2023 to 2024). The state of being infected such as from the introduction of a foreign agent such as serum, vaccine, antigenic substance or organism. "Since our data showed no MV destruction in sh VIL1 k/d C2BBe1 cells after STM infection, we suggest that villin after stimulation of PLCγ by Rac1-SopE is responsible to sever F-actin in MV." (PMID 36936760, 2023).
adenocarcinoma (1 paper, 2020). A common cancer characterized by the presence of malignant glandular cells. "We revealed that a panel with miR-192-5p, HNF1A-AS1 and VIL1 could accurately discriminate adenocarcinoma from normal cervix." (PMID 33024199, 2020). "We then plotted ROC curves for miR-192-5p/HNF1A-AS1/VIL1 panel as well as TCT tests in the 57 normal control group and 109 adenocarcinoma group." (PMID 33024199, 2020). "The expression of VIL1, HNF1A-AS1, MIR194-2HG, SSTR5-AS1, miR-192-5p, and miR-194-5p in adenocarcinoma were statistically significantly higher than that in normal control samples." (PMID 33024199, 2020). "In summary, our study has identified miR-192-5p/HNF1A-AS1/VIL1 panel that accurately discriminates adenocarcinoma from normal cervix." (PMID 33024199, 2020). "The expression of VIL1 mRNA, HNF1A-AS1, MIR194-2HG, SSTR5-AS1, miR-192-5p, and miR-194-5p were further investigated by RT-qPCR in another 57 normal cervical tissues and 141 adenocarcinoma tissues-." (PMID 33024199, 2020).
bacterial infection (1 paper, 2025). "Second, the Basal.MUC16 cluster showed a significant increase (adjusted p < 0.05) in genes associated with bacterial infection (PDZD3, SFTPA2, PIK3C2B), cytokine signaling (TRIM31, SERPINB2), and apoptosis (BCL2L15, VIL1)." (PMID 39935174, 2025).
renal disorders (1 paper, 2020). "Our results correlate well with the data obtained by other researchers in that blood APOA4, AAT, VIL1, complement component and cytokine concentrations increased in patients with renal disorders." (PMID 32046176, 2020).
VIL1 also shares sentences with these, for which no sentence is quoted: lung carcinoma (2 papers); Chronic colitis (1); diabetes (1); dysplasia (1); gastric adenocarcinoma (1); gastrointestinal infection (1); Intestinal Diseases (1); intestinal obstruction (1); large cell neuroendocrine carcinoma (1); large-cell neuroendocrine lung carcinoma (1); metabolic disorders (1); myocardial infarction (1); Parkinson’s (1); polyp (1); prostate carcinoma (1); small cell carcinoma (1); squamous cell carcinoma (1).